PLAG1 (PLAG1 zinc finger)
Diseases named in the same sentence as PLAG1 in open-access papers (continued):
Sharing a sentence is not in itself a finding about the gene and the disease.
CNS tumors (2 papers, 2023 to 2025). "A recently published case report presented another PLAG family gene alteration in the context of CNS tumors, namely one child and one adult with CNS tumors harboring gene fusions of PLAG1." (PMID 40751809, 2025). "Consequently, PLAG1 fusions expand the spectrum of the alterations encountered in CNS tumors." (PMID 37870637, 2023). "Molecular diagnostics, including DNA methylation profiling, methylation data-derived copy-number analysis, and RNA sequencing of pediatric CNS tumor samples, identified individual tumors harboring a gene fusion involving the PLAG family gene PLAG1 as the 3’ fusion partner." (PMID 40751809, 2025). "By t-SNE dimensionality reduction of DNA methylation profiles, PLAG1-fused tumors show a methylation pattern closely related to the one characteristic of PLAGL1- and PLAGL2-amplified tumors, but otherwise epigenetically distinct from all other described CNS tumor types." (PMID 40751809, 2025).
infection (1 paper, 2019). The state of being infected such as from the introduction of a foreign agent such as serum, vaccine, antigenic substance or organism. "The results showed that DYRK1A, FAM135A, PLAG1, ZNF148, and PHC3 were obviously inhibited at infection times of 3 h, 6 h, and 9 h pi." (PMID 31784561, 2019). "Downregulation of 4 miRNA target genes, including PLAG1, ZNF148, PHC3, and DYRK1A, was first found in CVB3-infected cells, though 4 genes were associated with nonenterovirus replication and infection." (PMID 31784561, 2019).
PLAG1 also shares sentences with these, for which no sentence is quoted: myxoid liposarcoma (4 papers); salivary gland neoplasm (3); lipoma (2); adenocarcinoma (1); Alzheimer disease (1); asthma (1); Azoospermia (1); clear cell carcinoma (1); CNS embryonal tumor (1); cognitive deficits (1); cylindroma (1); deafness (1); dentin dysplasia (1); dentinogenesis imperfecta (1); depression (1); dermatofibrosarcoma protuberans (1); endometrial stromal sarcoma (1); Ewing sarcoma (1); fibromyxoid tumor (1); Floating-Harbor syndrome (1); gestational diabetes (1); glioblastoma (1); growth failure (1); hidradenocarcinoma (1); hidradenoma (1); Hirschsprung disease (1); Hyperinsulinemia (1); Immunodeficiency (1); infectious disease (1); inflammatory myofibroblastic tumor (1).
A further 39 diseases each share a sentence with PLAG1 in 1 paper.